MN1 (MN1 proto-oncogene, transcriptional regulator)
Diseases named in the same sentence as MN1 in open-access papers (continued):
Sharing a sentence is not in itself a finding about the gene and the disease.
aortic valve disease (1 paper, 2026). "PDE3A and CDK8 have all been previously linked to cardiovascular disease or physiology, although not specifically to aortic valve disease, whereas the link between MN1 and cardiovascular disease remains largely unexplored." (PMID 41419685, 2026).
bladder cancer (1 paper, 2025). "To further elucidate the molecular mechanisms by which MN1 influences bladder cancer cell functions, we performed RNA sequencing on T24 cells with MN1 knockdown compared to control groups." (PMID 40308577, 2025). "We discovered that the XIST/miR-15a-5p/MN1/FZD2 signaling axis plays a significant role in regulating the progression of bladder cancer." (PMID 40308577, 2025). "The XIST/miR-15a-5p/MN1 signaling axis plays a critical role in the gender disparity observed in bladder cancer prognosis, particularly in women." (PMID 40308577, 2025). "Our findings indicate that XIST and MN1 promote the proliferation and migration of bladder cancer cells, while miR-15a-5p exerts inhibitory effects on these processes." (PMID 40308577, 2025). "In this study, we identified the critical role of the XIST/miR-15a-5p/MN1/FZD2 signaling axis in explaining gender disparities in bladder cancer prognosis." (PMID 40308577, 2025). "We evaluated the expression of the XIST/miR-15a-5p/MN1 axis in tissue samples from 50 male and 50 female bladder cancer patients." (PMID 40308577, 2025). "Rescue experiments showed that XIST influences the biological functions of bladder cancer cells by regulating MN1 expression." (PMID 40308577, 2025). "The XIST/miR-15a-5p/MN1/FZD2 signaling axis was found to play a critical role in promoting bladder cancer progression." (PMID 40308577, 2025). "In this study, we found that XIST might influence bladder cancer progression through the miR-15a-5p/MN1 signaling axis." (PMID 40308577, 2025). "Furthermore, we examined whether the impact of XIST on bladder cancer cell functions is mediated by MN1." (PMID 40308577, 2025). "Additionally, MN1 mRNA expression was significantly elevated in both female and male bladder cancer tissues relative to adjacent non-cancerous tissues, with a higher increase in females." (PMID 40308577, 2025). "However, the function of MN1 in bladder cancer has not been reported." (PMID 40308577, 2025).
brain malformations (1 paper, 2025). "In summary, all the obtained results indicate that the de novo deletion in 22q12.1 and the subsequent expression of the MN1-CPMER fusion transcript are causative for the fetal brain malformations." (PMID 40428419, 2025). "In the present study, a 58 kb heterozygous de novo deletion in 22q12.1 affecting the protein-coding gene MN1 and the lncRNA CPMER was detected in a male fetus as the cause of severe cerebral malformations." (PMID 40428419, 2025).
breast carcinoma (1 paper, 2023). "Similarly, drivers of oncogenesis in breast cancer and AML, IRS4, and MN1 are mutated and downregulated." (PMID 37091785, 2023).
cleft palate (1 paper, 2012). Cleft palate is a fissure type embryopathy that affects the soft and hard palate to varying degrees. "This suggests that deletion of MN1 in the six patients we describe may be causally linked to their cleft palates and/or craniofacial abnormalities." (PMID 22436304, 2012). "Additionally, Mn1 regulates maturation and function of calvarial osteoblasts and is an upstream regulator of Tbx22, a gene associated with murine and human cleft palate." (PMID 22436304, 2012). "Thus, our report describes a NF2-adjacent chromosome 22q12.2 deletion syndrome and is the first to report association of MN1 deletion with abnormal craniofacial development and/or cleft palate in humans." (PMID 22436304, 2012). "Taken together, this suggests that loss of MN1 in these six patients may be the underlying cause for, or contributing factor to, their craniofacial dysmorphism and/or cleft palate, and supports investigation of a role for MN1 in human craniofacial dysmorphism and/or cleft palate." (PMID 22436304, 2012).
Kenny-Caffey syndrome type 2 (1 paper, 2022). "Finally, ES revealed two additional alterations in individuals with syndromic CS–p.Arg1295* in the MN1 (P63), which was recently discovered, and subsequently linked to CS, and p.Arg305Gly in FAM111A (P136), resulting in Kenny-Caffey syndrome type 2, in which CS represents an unseen clinical feature." (PMID 35591945, 2022).
malignant mesothelioma (1 paper, 2016). A malignant neoplasm of the pleura or peritoneum, arising from mesothelial cells. "Although the Sanger method has limited sensitivity due to the rare mutant allele copies in heterogeneous cancer DNA samples, MN1 and PRG4 remain potential candidates responsible for the development and progress of malignant mesothelioma." (PMID 27187383, 2016).
mesothelioma (1 paper, 2023). A usually malignant and aggressive neoplasm of the mesothelium which is often associated with exposure to asbestos. "The MN1 anti‐MSLN antibody was used to stain a formalin‐fixed paraffin‐embedded tissue microarray of histologically confirmed mesothelioma from 75 consecutive patients who had undergone pleurectomy with or without decortication." (PMID 37040900, 2023).
neural tumors (1 paper, 2025). "MN1 is a chromatin remodeling factor and transcription co-regulator that plays a significant role in neural tumors." (PMID 40308577, 2025).
sarcoma (1 paper, 2021). A usually aggressive malignant neoplasm of the soft tissue or bone. "The histology and immunoprofile of EWSR1:PATZ1-fused sarcoma has also been described as incredibly polyphenotypic, but MN1:PATZ1-fused sarcomas have not yet been described." (PMID 34417833, 2021).
synovial sarcoma (1 paper, 2023). "While BAF complexes are critical in SS18-SSX-driven synovial sarcomas, we show that EWSR1 and MN1 activate gene expression via a mechanism that can be independent of BAF presence." (PMID 37735617, 2023).
tumor (24 papers, 2016 to 2026). "As a proof-of-principle, we here generated four novel R26 KI mice that enable conditional overexpression of 3 putative oncogenes (Jarid2, Runx2, MN1) and one dominant negative allele of a tumour suppressor (dnETV6), which all have been previously associated with the pathobiology of human leukemia." (PMID 31332244, 2019). "In six cases, the following matches were highlighted: one iHGG, two IDH wild-type, one BCOR internal tandem duplication (BCOR-ITD), one plexus tumor, and one MN1-rearrangement." (PMID 35204463, 2022). "In particular, this revaluation confirmed the one iHGG, one with NTRK-fusion, one BCOR-ITD, and the MN1-rearranged neoplasm already identified." (PMID 35204463, 2022). "In fact, all MN1-rearranged tumor patients in the cohort are currently alive, despite multiple tumor recurrences in some cases." (PMID 30876455, 2019). "Of note, MN1 exerts a pro-tumor effect through the XIST/miR-15a-5p/MN1/FZD2 signaling axis, and its significantly high expression is observed in female patients with poor prognosis, which may be an important molecular basis for the gender difference in BLCA." (PMID 41019085, 2025). "However, other rare oncogenic fusions such as MN1, PATZ1, BCOR and CIC do appear to be diagnostic for specific tumor types." (PMID 39409964, 2024). "However, and most notably, we observed that MN1 driven Pten null murine T-ALL/T-LBL tumours are characterized by increased levels of Lyl1, a marker of murine and human immature T-ALL24,28–31." (PMID 31332244, 2019). "The MN1 gene with two CAG repeat sets is a tumor suppressor." (PMID 27677590, 2016). "Factors such as tumor location (supratentorial vs. infratentorial), age at diagnosis, and the presence of molecular markers (e.g., FOXR2, BCOR, CIC, MN1 alterations) are important for differential diagnosis but are not definitive in isolation." (PMID 40647489, 2025). "Future research should incorporate mouse models to validate our zebrafish findings, investigate long-term tumor development, and explore the potential therapeutic interventions targeting the XIST/miR-15a-5p/MN1 axis in a mammalian context." (PMID 40308577, 2025). "Notably, this analysis revealed significantly higher Lyl1 expression levels in MPL tumours as compared to PL counterparts, suggesting that MN1 might, at least in part, be able to drive a more immature oncogenic transcriptional profile during Pten null-driven T-cell transformation." (PMID 31332244, 2019). "MN1 and EWSR1 are both involved in fusions in other tumor entities." (PMID 34417833, 2021). "Finally, and given that high MN1 expression is largely restricted to immature human T-ALLs22–26, we also analysed PL and MPL tumours for Lyl1 expression, a well-known marker of murine and human immature T-ALL24,28–31." (PMID 31332244, 2019). "Given that high MN1 expression has also been previously reported in immature subtypes of human T-ALL22–26, we also crossed the MN1 conditional KI mice into a Pten null tumour prone background." (PMID 31332244, 2019). "In our experience, two tumor diagnoses were revised based on the NGS finding of NAB2::STAT6 fusion (patient #32) and absence of MN1 alteration (patient #30)." (PMID 38440233, 2024). "No similarity was seen with the recently described HGNET_MN1 tumor type, which is characterized by MN1:BEND2 and MN1:CXXC5 (but not PATZ1) fusions." (PMID 34417833, 2021). "We, therefore, believe it to be likely that these MN1:PATZ1 and EWSR1:PATZ1 fusions are pathognomonic for this novel tumor type." (PMID 34417833, 2021).
cancer (9 papers, 2013 to 2025). A tumor composed of atypical neoplastic, often pleomorphic cells that invade other tissues. "RASGRP3 also has a physiological role in cancer, as does MN1, with both of these transcripts downregulated after both interventions." (PMID 31308645, 2019). "LUAD1 enriched for alterations in EGFR, MN1 and MYH9, LUAD2 enriched for BRCA2, while LUAD3 did not enrich for known cancer drivers." (PMID 35383171, 2022).
neurodevelopmental disorder (1 paper, 2025). A behavioral and cognitive disorder with onset during the developmental period that involves impaired or aberrant development of intellectual, motor, or social functions. "Additionally, MN1 is located in a craniofacial and neurodevelopmental disorders hotspot locus (Ch22q12 in humans), where deletions of varying lengths affect both exons and manifest by a broader phenotypic spectrum." (PMID 40424121, 2025).
MN1 also shares sentences with these, for which no sentence is quoted: ependymoma (7 papers); CNS tumors (4); medulloblastoma (2); pilocytic astrocytoma (2); breast and ovarian cancer (1); cardiovascular disease (1); chronic myelomonocytic leukemia (1); CNS embryonal tumor (1); dependence (1); embryonal tumors (1); ganglioglioma (1); Hydrocephalus (1); Hypertelorism (1); learning disabilities (1); malignant brain tumor (1); megakaryocytic leukemia (1); mesenchymal tumors (1); myelodysplastic syndrome (1); neuroblastoma (1); ovarian carcinoma (1); pulmonary diseases (1); soft tissue sarcoma (1); Thrombocytopenia (1).